GTSE1 (G2 and S-phase expressed 1)
Diseases named in the same sentence as GTSE1 in open-access papers (continued):
Sharing a sentence is not in itself a finding about the gene and the disease.
tumor (continued). "Our previous results showed that GTSE1 was upregulated in human HCC and influenced tumour progression." (PMID 28698581, 2017). "The GTSE1 protein was predominantly expressed in the nuclei and plasma of the HCC tumour regions (T), whereas GTSE1 was only occasionally expressed in the liver cells of the adjacent non-cancerous tissues (N)." (PMID 28698581, 2017). "First, in our previous analysis of differential gene expression, no obvious disparities in GTSE1 expression levels were observed when compared tumor tissues to normal tissues among patients with PAAD and PCPG." (PMID 38715380, 2024). "Additionally, while investigating the relationship between GTSE1 and immune infiltration in LUAD cells, some studies have examined the relationship between GTSE1 and immune-related cells and functions in other tumor cells." (PMID 39629227, 2024). "GTSE1 and PRR11 have been reported in various types of tumor." (PMID 32180800, 2020). "Since GTSE1 overexpression was observed in HCC tissues and cells, our next question is whether GTSE1 had a direct functional role in facilitating tumor growth in HCC." (PMID 27240802, 2016). "Notably, no studies have been found regarding the involvement of GTSE1 in tumor development regulation through ubiquitin-mediated protein degradation." (PMID 39629227, 2024). "Notably, the depletion of GTSE1 leads to the upregulation of KLF4, a tumor suppressor in KIRC." (PMID 38464749, 2024). "Thus, GTSE1 may play an important role in HCC cell migration and invasion that is very important for tumor metastasis." (PMID 27240802, 2016). "Moreover, the GTSE1 mRNA expression level is positively correlated with MKI67, which was consistent with the results of the protein level, suggesting that GTSE1 may be a potential tumor marker for prognosis." (PMID 30961661, 2019). "GTSE1 is not the only gene involved in cell migration to be regulated by these two pathways, suggesting that they are profoundly interconnected in regulating processes required for cell proliferation but also for other aspects of tumor progression such as invasion and metastasis." (PMID 28978043, 2017). "Spermatogenesis associated 18 (SPATA18) and EF-hand domain family member D1 (EFHD1), as opposed to SPOCK1, GTSE1 and ADAM12, are two tumor suppressors both involved in mitochondria functions." (PMID 37370817, 2023).
GTSE1 also shares sentences with these, for which no sentence is quoted: colon cancer (4 papers); lung squamous cell carcinoma (3); renal cell carcinoma (3); clear cell renal cell carcinoma (2); esophageal squamous cell carcinoma (2); acral melanoma (1); acute myeloid leukemia (1); Azoospermia (1); cholangiocarcinoma (1); colon adenocarcinoma (1); colorectal NETs (1); esophageal malignant tumor (1); gastric tumours (1); Hydrocephalus (1); infection (1); kidney chromophobe (1); laryngeal squamous cell carcinoma (1); lung adenoma (1); metastatic tumors (1); nasopharyngeal carcinoma (1); non-small cell lung carcinoma (1); pancreatic adenocarcinoma (1); paraganglioma (1); pheochromocytoma (1); primary immunodeficiency (1); rectum adenocarcinoma (1); thyroid carcinoma (1).